SLC1A5 (solute carrier family 1 member 5)
Diseases named in the same sentence as SLC1A5 in open-access papers (continued):
Sharing a sentence is not in itself a finding about the gene and the disease.
tumor (continued). "Taken together, these findings demonstrated the presence of a strong correlation of SLC1A5 expression with prognosis and tumor immunology in LGG and HCC." (PMID 34367941, 2021). "Among the selected transporters, expression of ASCT2 (SLC1A5), which is important for maintaining glutamine levels in tumor cells, was downregulated at both the mRNA and protein level in Huh7 cells." (PMID 34796113, 2021). "To investigate the prognostic ability of SLC1A5/TALDO1 co-expression independently of tumor size, grade and nodal stage, we performed multivariate Cox regression." (PMID 34282517, 2021). "Preclinical evaluation of another SLC1A5 marker, 4-[18F]Fluoro-Gln in lung cancer xenograft models showed a tumor-specific accumulation compared to normal lung tissues." (PMID 33401748, 2021). "SLC1A5 represents a useful prognostic biomarker in multiple cancers, and its expression correlates highly with tumor immune-cell infiltration, especially in HCC and LGG." (PMID 34367941, 2021). "Specially for LGG and HCC, SLC1A5 can be used to evaluate the extent of immune cell infiltration in the tumor tissues." (PMID 34367941, 2021). "Patients with higher SLC1A5 tumor levels in METABRIC had an unfavorable outcome compared with those patients with low SLC1A5 levels (P < 0.05)." (PMID 34282517, 2021). "Another tumor suppressor, retinoblastoma (Rb), can directly regulate the glutamine transporter ASCT2 (SLC1A5) to reduce glutamine uptake via the transcription factor E2F3." (PMID 33511116, 2020). "Nonetheless, we were able to confirm upregulated expression of LAT1 following chronic ADT at both protein and mRNA levels, while ASCT2 (SLC1A5) expression was at low level in 22Rv1 CRPC tumours under chronic ADT." (PMID 33237350, 2020). "SLC1A4 and SLC38A2 (alanine transporter) and SLC1A5 (ASCT2-glutamine transporter) enhance PDAC tumor growth by importing essential amino acids and therefore represent additional potential therapeutic targets." (PMID 33198082, 2020). "Tumour-infiltrating FOXP3 + lymphocytes and CD68 + macrophages were both predominant in tumours with high SLCs and to a lesser extent in those tumours with high SLC1A5 expression (p < 0.0001)." (PMID 31819174, 2020). "Inhibitors have been developed for the glutamine uptake transporter SLC1A5 (ASCT2), which is upregulated across many tumour types to increase glutamine uptake." (PMID 33092283, 2020). "SLC7A5 and SLC3A2 were expressed at relatively high levels in 22Rv1 castration-resistant orthografts following chronic ADT (modelling clinical castration-resistant disease), while SLC1A5 was preferentially expression in CWR22Res tumours following acute ADT." (PMID 33237350, 2020). "Both GLUT1 and SLC1-A5 have been suggested to facilitate tumor progression and are transactivated directly by PPAR beta/delta." (PMID 32855630, 2020). "SLC7A5 and SLC1A5 mRNA expression was consistent with that observed at protein level, i.e. elevated SLC7A5 and reduced SLC1A5 levels in the castration-resistant 22Rv1 tumours." (PMID 33237350, 2020). "Dependence of leukemic cells on glutamine for tumor growth has been reported, and knockdown of the glutamine transporter SLC1A5 abrogates tumor development in mice." (PMID 31319822, 2019). "Tumor cells that overexpressed SLC1A5 displayed higher uptake and retention of the 18F-labeled [2S,4R] stereoisomer of glutamine." (PMID 31652923, 2019). "Tumor cells achieve high intracellular concentrations of glutamine primarily through upregulation of glutamine transporters including SLC1A5 and SLC7A5." (PMID 31652923, 2019). "SLC1A5 has been shown to interact with oncogenes and/or tumor-suppressor genes to mediate tumor progression." (PMID 29562706, 2018). "SLC7A5 is co-expressed with the glutamine transporter, SLC1A5, in many cancers suggesting a functional coupling of these transporters in supporting tumour progression." (PMID 29566741, 2018).
tumor (continued). "In a multivariable logistic regression analysis FIGO-stage (OR = 12.4), tumor grade (OR = 5.1) and SLC1A5 positivity (OR = 0.1) were independent predictive factors for recurrent disease." (PMID 28609484, 2017). "During tumor progression tumor cells overcome the allowed number of normal cell doubling, and SLC1A5 is known to be a part of this process." (PMID 28609484, 2017). "We found that low-dose PTX down-regulated glutaminolysis-related genes (GLS, SLC7A11 and SLC1A5) and increased lactate production, resulting in decreased pH of the tumor microenvironment which inhibited tumor cell growth." (PMID 28522974, 2017). "Coupled with the discovery that the glutaminolytic switch is promoted by oncogenes and inhibited by tumor suppressors, this has driven the search for SLC1A5 inhibitors." (PMID 28553292, 2017). "Knockdown SLC1A5 significantly suppressed the xenograft tumor growth when compared to the control group." (PMID 29100325, 2017). "The FIGO-stage, tumor grade and SLC1A5 status were all independent predictive factors for recurrent disease." (PMID 28609484, 2017). "The expression of SLC1A5 was mainly appeared in the membrane of tumor cells and the staining intensity and distribution were variable in different specimens." (PMID 26599282, 2015). "SLC1A5 expression was significantly upregulated in tumor tissues when compared with corresponding peri-tumor tissues (P = 0.003) and normal kidney tissues (P = 0.007)." (PMID 26599282, 2015). "Knocking down SLC1A5 [Solute Carrier Family 1 (Neutral Amino Acid Transporter), Member 5], the glutamine transporter has been demonstrated to inhibit tumor formation in acute myeloid mouse xenotransplant model." (PMID 26140362, 2015). "Consistent with the functions exerted by glutamine, SLC1A5 is profoundly involved in uptake of essential amino acids, activation of mTORC1 and glutamine-dependent tumor cell survival and growth." (PMID 26599282, 2015). "To further evaluate the protein level of SLC1A5 in ccRCC tumor tissues, we detected the expression of SLC1A5 by immunohistochemical staining analysis in 187 patients with ccRCC." (PMID 26599282, 2015). "In addition, tumor cells upregulate glutamine transporters, such as solute carrier family 1 member 5 (SLC1A5) and glutaminase (GLS), to enhance glutamine uptake and utilization." (PMID 40223597, 2025). "In HNSCC, high expression of SLC1A5 is associated with reduced CD8+ T cell infiltration, suggesting that SLC1A5 may suppress tumor immunity by modulating glutamine metabolism." (PMID 40821122, 2025). "The results showed that SLC1A5/SLC3A2/SLC7A5 knockdown diminished tumor growth in vivo." (PMID 39757767, 2025). "We also found that c‐Myc overexpression elevated SLC1A5/SLC3A2/SLC7A5 expression in RTN4IP1‐deficient cells, and promoted cell proliferation as well as tumor growth upon RTN4IP1 knockdown, demonstrating the essential role of SLC1A5/SLC3A2/SLC7A5 in RTN4IP1‐mediated cell proliferation." (PMID 39757767, 2025). "Although the consequences of blocking SLC1A5 in luminal B tumours remain undetermined, our data suggest that SLC1A5 could be used as a target in luminal B tumours to reduce Gln uptake and thus cell proliferation and growth." (PMID 39843491, 2025). "Concurrently, based on the evidence linking fatty acid and glutamine metabolism to tumor progression, therapeutic strategies targeting SLC1A5 or CD36 could be integrated with existing chemotherapy or immunotherapy to potentially enhance therapeutic efficacy." (PMID 41212437, 2025). "Nevertheless, the present study exposed that concurrent blockade of the glutamine transporter alanine‐serine‐cysteine type 2 (ASCT2, encoded by SLC1A5) and GLS1 could generate significant anti‐tumor activity with a manageable safety profile." (PMID 39680480, 2025).
tumor (continued). "Although drugs targeting ATF4-Gln axis (e.g., DHA [dihydroartemisinin] inducing ATF4 degradation, SLC1A5 monoclonal antibodies) show efficacy in preclinical studies, they face challenges including metabolic plasticity, tumor heterogeneity, and toxicity to normal tissues." (PMID 40830338, 2025). "High SLC1A5 protein expression (> 40 H-score) was observed in 63% of the tumours." (PMID 39843491, 2025). "Additionally, another Gln transporter, SLC1A5, is highly expressed in triple-negative breast cancer patients, correlating with poor survival in tumor-bearing mice." (PMID 40723225, 2025). "We further demonstrated that the association of SLC1A5 with patient outcome occurs only in luminal B and not luminal A tumours." (PMID 39843491, 2025). "It was shown that miR23a (miroRNA23a) and miR 24b could suppress the expression of the SLC1A5 gene by reducing glutamine metabolism in the tumor." (PMID 39125992, 2024). "Besides, YY1, SLC1A5, and Bcl-2 protein levels are significantly reduced, while Bax protein level is markedly enhanced in the tumor tissues of Silibinin-treated group." (PMID 38410123, 2024). "Therefore, SLC1A5-high tumor cells undergo substantial changes in cell proliferation and cell cycle-associated genes to promote HNSCC progression." (PMID 39223142, 2024). "SLC1A5 overexpression abolishes the anti-tumor effect of Silibinin in GBM cells." (PMID 38410123, 2024). "Metabolic reprogramming of tumor cells in the TME promotes the expression of L-glutamine transporters ASCT2(SLC1A5) and SN2(SLC38A5), alongside glutamic acid–metabolizing enzymes (e.g., glutaminase [GLS]), glutamine synthetase, and aminotransferases, thereby increasing L-glutamine intake." (PMID 39227970, 2024). "Moreover, IHC staining shows a significant reduction in the number of Ki67, YY1, and SLC1A5-positive cells in the tumor tissues of the Silibinin-treated group." (PMID 38410123, 2024). "SLC1A5, as an efficient transporter of glutamine, could strengthen the metabolic capabilities and effector functions of tumor-directed CAR-NK and T cells." (PMID 39958609, 2024). "Therefore, SLC1A5 is an intrinsic factor regulating tumor growth and an extrinsic factor modulating the immune profile in TME." (PMID 39223142, 2024). "As a result, SLC1A5 suppresses tumor growth by supporting ferroptosis." (PMID 36902506, 2023). "Tumor proliferation stimulates upregulation of the glutamine transporter ASCT2/SLC1A5 and the GLUL." (PMID 37420266, 2023). "Overexpression of SLC1A5 restores the attenuation of tumour metastasis by NDRG2." (PMID 37829798, 2023). "V-9302, an SLC1A5 antagonist, elicited a marked anti-tumour response in preclinical tumour models." (PMID 37241864, 2023). "Additionally, SLC1A5 accelerates the growth of lung and colorectal malignancies by forcing tumor cells to undergo metabolic reprogramming." (PMID 37818360, 2023). "In addition, immunofluorescence (IF) staining showed that SLC1A5 was mainly distributed and localized in the cell membrane of A-431 and U251 tumor cell lines." (PMID 37566748, 2023). "Considering that SLC1A5 is a receptor, we took a series of experiments to test whether SLC1A5 affects the function of tumor cells." (PMID 37818360, 2023). "Moreover, SLC1A5 has been shown to mediate uptake of glutamine, which is a conditionally essential amino acid used in rapidly proliferating tumor cells." (PMID 35041678, 2022). "Targeting SLC1A5 has been considered as a potential strategy to strengthen anti-tumor immunity." (PMID 36566214, 2022). "SLC1A5, a glutamine transporter, can control glutamine uptake and is essential for tumor growth." (PMID 36273140, 2022).
tumor (continued). "Moreover, SLC1A5 expression was markedly elevated in high-stage NB tumor samples compared with low-stage ones and it was significantly associated with poor prognosis and low survival of NB patients." (PMID 35406574, 2022). "Also, a significant reduced SLC1A5 protein expression was discovered in the tumor tissues of sh-circ_0000808 group." (PMID 36192755, 2022). "At the in vivo level, SLC1A5 deletion inhibited tumor growth in a mice xenograft model." (PMID 35419359, 2022). "SLC1A5 inhibitor combined with an immune checkpoint inhibitor could synergistically relieve tumor immunosuppression and inhibit tumor growth." (PMID 36566214, 2022). "SLC1A5 has been regarded as an oncogene by the mTORC1 signaling pathways or KRAS mutation in certain tumors, and loss of SLC1A5 may inhibit tumor growth." (PMID 36262284, 2022). "Additionally, the growth of tumor xenografts is suppressed by berberine and the SLC1A5 expression and c-Myc." (PMID 36144625, 2022). "In addition, SLC1A5 acts as a high-affinity transporter of L-glutamine to enhance the growth of epithelial and tumor cells in culture." (PMID 36081504, 2022). "In addition, SLC1A5 is significantly increased in various neoplasms, indicating that SLC1A5 is closely related to human physiological functions and many major diseases." (PMID 35874898, 2022). "At the in vivo level, silencing SLC1A5 markedly suppressed the xenograft tumor growth." (PMID 35419359, 2022). "In addition to glutamine consumption, elevation of SLC1A5 indicates increase of glutamine uptake which makes sense that tumor cell growth requires more glutamine as well." (PMID 35058981, 2022). "Transfection of si-SLC1A5 reduced SLC1A5 content in tumor cells." (PMID 36273140, 2022). "In addition, overexpression of hsa_miR-370-3p decreased SLC1A5 content in tumor cells, and hsa_miR-370-3p absence displayed the opposite effect." (PMID 36273140, 2022). "Therefore, it indicated that SLC1A5 suppressed anti-tumor immunity despite increased immune cell mobilization." (PMID 36566214, 2022). "Other than SLC1A5-mediated glutamine transport, glutamine could also be synthetized by glutamine synthetase by tumor cells." (PMID 36010849, 2022). "Since SLC1A5 has abilities to transport glutamine required for cell proliferation and to inhibit ferroptosis by promoting a-ketoglutarate synthesis, it has become a hotspot in tumor research in recent years." (PMID 35419359, 2022). "As a result, SLC1A5 is capable of inhibiting tumor growth by supporting ferroptosis." (PMID 35419359, 2022). "Our study found seven downstream factors that may be associated with chemoresistance, LTF, SOD2, STAT1, CDKN2A, CD81, RAC1, and NDRG1 and five factors that may be associated with tumor development, CCN1, DCTN3, MUC1, H1-5, and SLC1A5." (PMID 35421932, 2022). "The high expression of SLC1A5 could reduce oxidative stress damage under tumor hypermetabolism through increasing the expression of GPX4, which further accelerates cell proliferation and malignant progression." (PMID 36566214, 2022). "SLC1A5 expression and its effect on tumor prognosis were analyzed using multiple online tools Oncomine, Gene Expression Profiling Interactive Analysis, PrognoScan, and Kaplan-Meier plotter with their own datasets as well as the data from The Cancer Genome Atlas." (PMID 34367941, 2021). "Moreover, tumours with high SLC38A2 expression were also commonly represented in the poor prognostic high SLC cluster (SLC1A5+/SLC7A5+/SLC3A2+)." (PMID 33028955, 2021). "The significant reduction of LDHA and SLC1A5 protein expression in Fraction B treated tumor may represent additional layer of action or regulation and deserves further investigation." (PMID 34349642, 2021). "The correlations between SLC1A5 and tumor immune infiltrates were determined via TIMER." (PMID 34367941, 2021). "As an alternative carbon source, tumour cells may use glutamine, which can be transported into the cell by the solute carrier family 1 member 5 (SLC1A5)." (PMID 34968247, 2021).
tumor (continued). "Furthermore, we explored the correlation of SLC1A5 expression with immune infiltration via the Tumor Immune Estimation Resource (TIMER) and GEPIA databases." (PMID 34367941, 2021). "Targeting SLC1A5 in in vivo experiments also reduced tumor growth in NSCLC xenografts." (PMID 35223460, 2021). "Moreover, the correlation between SLC1A5 expression and the marker genes of immune cells implicate SLC1A5 in regulating tumor immunology in LGG and HCC." (PMID 34367941, 2021). "In this study, we observed that Fraction B not only significantly suppressed the expression of key enzymes responsible for glycolysis, LDHA, and glutamine transporter, SLC1A5, in the tumor tissues, but also reduced the metabolites of glycolysis and glutamine levels." (PMID 34349642, 2021). "Inhibition of SLC1A5 effect can lead to the reduction of tumor cell growth and proliferation." (PMID 34054543, 2021). "SLC1A5 has a key role in sustaining glutamine metabolism and tumor growth and progression." (PMID 34282517, 2021). "SLC1A5 may serve as a potential target for enhancing anti-tumour immunity in the tumour microenvironment." (PMID 34760691, 2021). "In addition, BBR inhibits the growth of tumor xenografts and the expression of SLC1A5 and c-Myc in vivo." (PMID 34885950, 2021). "In line with this, the lactate levels increased both in tumor and peritumoral tissues, as well as the expression of glutamine transporters (i.e., SLC1A5) and glycolytic enzymes, such as glucose-6-phosphate isomerase (GPI), phosphoglycerate kinase (PGK1), aldolase A (ALDOA) and hexokinase 2 (HK2)." (PMID 33924061, 2021). "Furthermore, SLC1A4/SLC1A5, the main transporters of serine, are upregulated in serine-dependent tumor cells." (PMID 33269112, 2020). "In adenocarcinomas, SLC1A5 mRNA expression correlated with tumor size (r(p) = 0.41, P = 0.005)." (PMID 31668020, 2019). "xCT/SLC7A11 transporter uptakes cystine in exchange for glutamine, which is essential for reduced form of glutathione (GSH) synthesis to reduce reactive oxygen species (ROS) in the tumor microenvironment, while ASCT2/SLC1A5 transporter uptakes glutamine in a collaborative manner with xCT/SLC7A11." (PMID 30053872, 2018). "As observed, in tumor tissues, 51.4% (36/70) of the cases showed ‘‘higher expression’’ of SLC1A5." (PMID 29100325, 2017). "Compared to adjacent tissues, SLC1A5 highly expressed in the tumor tissues." (PMID 29100325, 2017). "However, the GC tissues with higher expressed SLC1A5 had inclination towards larger tumor size (P < 0.05), deeper local invasion (P < 0.001), more lymph node metastasis (P < 0.05), advanced TNM stage (P < 0.05) and high Ki-67 expression (P < 0.01)." (PMID 29100325, 2017). "As glutamine is an important immunomodulatory nutrient, SLC1A5 also has been determined to involve in inflammatory T cell responses, which might exert key functions in tumor immunity." (PMID 26599282, 2015). "In addition, Silibinin reduces GBM tumor growth by regulating YY1/SLC1A5 pathway." (PMID 38410123, 2024). "Notably, SLC1A5 KO mice are developmentally normal, although they do present with some immunological defects that could impact tumor immunity." (PMID 39068660, 2024). "Reductions of GLS1 and SLC1A5 could induce decrease of glutaminolysis and glutamine uptake which will finally result in reduction of energy supplies and tumor suppression through inducing tumor cell apoptosis." (PMID 35058981, 2022). "Moreover, IHC staining was performed on the tumor tissues of each group, and the results showed that the positive cells of SLC1A5 and ki67 were decreased, while the positive cells of Bax and E-cadherin were increased in the tumor tissues of sh-circ_0000808 group." (PMID 36192755, 2022). "Moreover, SLC1A5 may play an important role in the microenvironment of STAD by regulating tumor infiltration by immune cells." (PMID 35305616, 2022).